CSTF2 (cleavage stimulation factor subunit 2)
Description:
One of the multiple factors required for polyadenylation and 3'-end cleavage of mammalian pre-mRNAs. This subunit is directly involved in the binding to pre-mRNAs.
Synonyms: CstF-64; CSTF64; XLID113
Tractability: PROTAC: UniProt records ubiquitination sites on it; ubiquitination databases record sites on it; its protein half-life has been measured.
Gene: Protein-coding gene on chromosome X (100,820,369 to 100,841,523, forward strand). Ensembl gene ENSG00000101811.
Subcellular location: Nucleus
Subcellular location (Human Protein Atlas): Nucleoplasm; Nuclear bodies
Pathways (Reactome):
Metabolism of RNA: Processing of Intronless Pre-mRNAs; mRNA 3'-end processing; mRNA Polyadenylation; tRNA processing in the nucleus
Disease: Dengue Virus-Host Interactions
Gene expression (Transcription): RNA Polymerase II Transcription Termination
Gene Ontology:
Molecular function: protein binding; RNA binding; nucleic acid binding
Biological process: mRNA 3'-end processing; regulation of mRNA 3'-end processing; nuclear histone mRNA catabolic process; cellular response to nerve growth factor stimulus
Cellular component: cleavage body; mRNA cleavage and polyadenylation specificity factor complex; mRNA cleavage stimulating factor complex; nuclear body; nucleoplasm; nucleus; mRNA cleavage factor complex
Homologues: Orthologues: chimpanzee CSTF2 (100% identical), macaque CSTF2 (99% identical), dog CSTF2 (96% identical), guinea pig CSTF2 (96% identical), pig CSTF2 (95% identical), rabbit CSTF2 (95% identical), mouse Cstf2 (94% identical), rat Cstf2 (93% identical), tropical clawed frog cstf2 (66% identical), zebrafish cstf2 (61% identical), Drosophila melanogaster CstF64 (41% identical), Caenorhabditis elegans cpf-2 (28% identical), and 1 more. Paralogues in human: CSTF2T (75% identical), RBMX2 (14% identical), U2AF2 (13% identical), ZCRB1 (9% identical), UHMK1 (7% identical).
Diseases named in the same sentence as CSTF2 in open-access papers:
CSTF2 is named in the same sentence as 34 diseases in open-access papers, as found by Europe PMC text mining. Sharing a sentence is not in itself a finding about the gene and the disease. The quoted sentences say what the papers report.
lung cancer (12 papers, 2013 to 2025). A malignant neoplasm involving the lung. "Research has shown that APA of the CSTF2 is associated with lung cancer prognosis, and miRNA-21 is related to the prognosis of metastatic colorectal cancer." (PMID 40141449, 2025). "Expression of CSTF2 is associated with shortening of the 3′-UTR of differentially expressed genes in lung cancer." (PMID 35370655, 2022). "More importantly, CSTF2 overexpression was associated with poor prognosis for lung cancer patients." (PMID 24358221, 2013). "CSTF2 is often trans-activated in most primary lung cancers and is often overexpressed in clinical lung cancer specimens and cell lines." (PMID 35370655, 2022). "For example, Aragaki and colleagues found that the CSTF2 was highly expressed in lung cancer, whereas its expression was scarcely detectable in any of 29 normal human tissues except testis." (PMID 24358221, 2013). "In addition, the overexpression of CSTF2 appears to promote the growth and invasion of lung cancer cells." (PMID 35875122, 2022). "We thus hypothesize that the CSTF2 gene may play a key role in regulation of 3′UTR length in lung cancer cells." (PMID 31391087, 2019). "Our data present in this study showed that the expression of CSTF2 correlates to the shortening of 3′UTR of the differentially expressed genes in lung cancer, and the results from this study suggest a clinic potential of CSTF2 as a therapeutic target for lung cancer." (PMID 31391087, 2019). "There is a significant correlation between CSTF2 and poor prognosis for lung cancer patients." (PMID 28320388, 2017). "Furthermore, the knockdown of CSTF2 by siRNA inhibited the growth of lung cancer cells." (PMID 24358221, 2013). "Cleavage stimulation factor 2 (CSTF2), an important regulator of APA, has been reported to have a tumorigenic function in urothelial carcinoma of the bladder and lung cancers." (PMID 35875122, 2022). "In H460 cells, down-regulation of CSTF2 resulted in an extension of the 3′ UTR of the shortened gene found in tumor tissues of NSCLC, suggesting that CSTF2 may be a therapeutic target for lung cancer." (PMID 35370655, 2022). "Our results also revealed that regulatory role of CSTF2, a polyadenylation processing protein, on the shortening of 3′UTR of these cancer-related genes, and a potential of CSTF2 as a therapeutic target for lung cancer." (PMID 31391087, 2019). "Even though the functional role of CSTF2 has not been conclusively proven, the overexpression results in the shortening of 3′ UTRs and promotes pathogenesis and poor prognosis in several types of cancer, including endometrial carcinoma, lung cancer, and bladder cancer." (PMID 35111149, 2021). "The negative correlation between the mRNA level expression of CSTF2 and the 3′ UTR length led to the suggestion that overexpression of this 3′ end processing factor plays a role in lung cancer." (PMID 29592812, 2018).
urothelial carcinoma of the bladder (6 papers, 2020 to 2022). "For instance, CSTF2 is upregulated in colon adenocarcinoma, liver cancer, uterine corpus endometrioid carcinoma, bladder urothelial carcinoma, breast invasive carcinoma, and lung adenocarcinoma." (PMID 35412944, 2022). "For example, CFIm25 causes 3′UTR shortening of a number of genes in glioblastoma cells and promotes tumor suppression; however, CSTF2 in urothelial carcinoma of the bladder elicits 3′UTR shortening of RAC1 and contributes to UCB pathogenesis." (PMID 33648552, 2021). "As a vital cleavage/polyadenylation factor, CSTF2 can shorten the length of 3’UTR RAC1 in human urothelial carcinoma of the bladder by mediating slow transcriptional elongation at RAC1." (PMID 34195183, 2021). "In contrast, activation of CSTF2 was observed to enhance the oncogenic activities in urothelial carcinoma of the bladder." (PMID 33648552, 2021). "In urothelial carcinoma of the bladder, CSTF2 over-expression results in recruitment to GUAAU motifs at the proximal PAS of the Rac family small GTPase 1 (RAC1) promoting their use and subsequent 3′UTR shortening." (PMID 32560344, 2020). "Moreover, CSTF2 activation has been shown to promote oncogenic activities in urothelial carcinoma of the bladder." (PMID 35412944, 2022). "Studies have shown that CSTF2 induces shortening of RAC1 3′-UTR and promotes urothelial carcinoma of the bladder." (PMID 35370655, 2022). "A recent study showed that high level of CSTF2 induces the shortening of RAC1 3’UTR, which is beneficial to the tumorigenesis of the urothelial carcinoma of the bladder." (PMID 35875122, 2022).
bladder cancer (4 papers, 2017 to 2021). "CSTF2 has previously been implicated as a promoter of lung and bladder cancer, through the regulation of ERBB2 and RAC1 3′ UTRs, respectively." (PMID 32029502, 2020). "Moreover, CSTF2, POLA1, HMOX2, and EFNB2 may be associated with the prognosis of bladder cancer patient." (PMID 28320388, 2017). "All of these results might indicate that CSTF2 and EFNB2 were two important protective factors in the prognosis of bladder cancer." (PMID 28320388, 2017). "HMOX2 (heme oxygenase-2), CSTF2 (cleavage stimulation factor, 3′ pre-RNA, subunit 2, 64 kDa), and POLA1 (polymerase (DNA directed), alpha 1) were the three obviously significant related genes, and a marginal significant correlation was found between EFNB2 (ephrin-B2) and prognosis of bladder cancer." (PMID 28320388, 2017).
breast carcinoma (4 papers, 2013 to 2025). "It was observed that the expression of several 3′-processing factors, including CPSF1 and CSTF2, were overall higher in breast cancer than normal cell lines, so this may be another important factor influencing APA pattern differences between MCF-7 and MCF-10A." (PMID 23437281, 2013). "Furthermore, cleavage stimulation factor subunit 2 (CSTF2) has been found to assist in alternative polyadenylation-induced shortening of the 3′UTR of HuR mRNA, which is essential for increased HuR translation in tamoxifen-resistant (TAMR) estrogen receptor-positive breast cancer." (PMID 38328550, 2024).
glioblastoma (3 papers, 2018 to 2025). The most malignant astrocytic tumor (WHO grade IV). "The interaction between ADAR1 and CSTF2 may have further implications as was suggested in glioblastoma cells." (PMID 40381037, 2025). "Our findings are supported by previous observations that PTBP1 acts antagonistically to CSTF2, repressing PAS usage, and that increased PTBP1 expression, as we observed in glioblastoma tumors, promotes proliferation and migration in glioblastoma cell lines." (PMID 29592812, 2018).
hepatocellular carcinoma (3 papers, 2021 to 2024). A malignant tumor that arises from hepatocytes. "However, the tumor-promoting role of CSTF2 in hepatocellular carcinoma (HCC) and its underlying molecular mechanism remains unclear." (PMID 35875122, 2022). "Interestingly, CSTF2 promotes hepatocellular carcinoma progression and drives glycolysis and lactate production." (PMID 38982038, 2024).
breast invasive carcinoma (2 papers, 2022). "The results showed that the expression of CSTF2 in breast invasive carcinoma, head and neck cancer, and liver hepatocellular carcinoma was significantly higher than that in adjacent tissues; however, the difference was not significant in colon adenocarcinoma." (PMID 35370655, 2022).
liver cancer (2 papers, 2022). An epithelial or non-epithelial malignant neoplasm that arises from the liver. "Results of the overall survival curve and progression-free survival curve showed that CSTF2 had a considerable impact on the prognosis of patients with kidney cancer, glioma, liver cancer, pancreatic cancer, melanoma, and other cancer types (p-values < 0.01)." (PMID 35370655, 2022).
pancreatic cancer (2 papers, 2022 to 2023). "The mRNA expression levels of CSTF2, FAF2, KIF20B, AKR1A1, APOM, KRT6C, and CD70, which were included in the prognostic model, were detected in different types of pancreatic cancer cell lines." (PMID 38268915, 2023). "Indeed, there are extremely few high-quality mechanistic studies on other signature genes (e.g., CSTF2, APOM, and KRT6C) that may serve as targets for subsequent studies on the molecular mechanisms of pancreatic cancer." (PMID 38268915, 2023).
cervical cancer (1 paper, 2021). A primary or metastatic malignant neoplasm involving the cervix. "RPP25, BARD1, BRCA1, CD3EAP, CSTF2, DARS2 and DNMT3B was up-regulated in most of cervical cancer tissues compared with corresponding normal cervix tissues." (PMID 34863153, 2021).
colon cancer (1 paper, 2020). "NUDT21, CPSF3, CSTF2, and MTPAP were overexpressed while PCF11 and PABPN1 were suppressed in colon cancer tissues." (PMID 32153636, 2020).
colorectal cancer (1 paper, 2025). A primary or metastatic malignant neoplasm that affects the colon or rectum. "Notably, SRSF3, CPSF3, FIP1L1, CTR9, NUDT21, and CSTF2, among others, were found to exhibit a more significant contribution to the differential 3′-UTR gene expression in colorectal cancer." (PMID 40702779, 2025).
non-small cell lung carcinoma (1 paper, 2022). A group of at least three distinct histological types of lung cancer, including non-small cell squamous cell carcinoma, adenocarcinoma, and large cell carcinoma. "For instance, CSTF2, as one of the components, was demonstrated to be correlated with poor prognosis of patients with non-small cell lung cancer (NSCLC)." (PMID 35412944, 2022).
ovarian carcinoma (1 paper, 2020). A malignant neoplasm originating from the surface ovarian epithelium. "CSTF2 mRNA expression was low or absent in most normal tissues suggesting that the presence of autoantibodies to this protein was reflective of its dysregulated expression in ovarian cancer." (PMID 32092936, 2020).
pancreatic ductal adenocarcinoma (1 paper, 2023). An infiltrating adenocarcinoma that arises from the epithelial cells of the pancreas. "Here, the authors perform transcriptomic m6A profiling to identify two subtypes of pancreatic ductal adenocarcinoma with differential m6A modifications and different clinical outcomes, which is driven by m6A regulator CSTF2." (PMID 37816727, 2023).
thyroid cancer (1 paper, 2022). "We analyzed CSTF2 expression in relation to more than 40 common immune checkpoint genes, showing that CSTF2 expression is associated with common immune checkpoints in a variety of cancers, especially in kidney, liver, and thyroid cancers." (PMID 35370655, 2022).
urothelial carcinoma (1 paper, 2021). A malignant neoplasm derived from the transitional epithelium of the urinary tract (urinary bladder, ureter, urethra, or renal pelvis). "CSTF2 induces 3′‐UTR shortening of Rac family small GTPase 1 (RAC1) to exacerbate cellular malignancy in urothelial carcinoma." (PMID 34586744, 2021).
cancer (23 papers, 2008 to 2025). A tumor composed of atypical neoplastic, often pleomorphic cells that invade other tissues. "Loss of Kindlin-1 leads to increased tumor growth, with many of the most upregulated genes in the Kindlin-1-depleted tumors linked to cancer prognosis, including Cstf2, Ppp1r10, Nr4a1 and Ggt1." (PMID 38982038, 2024). "The diagnostic and prognostic value of CSTF2 in a pan-cancer analysis was also evaluated in hopes to find new diagnostic biomarker and target for the treatment of tumors." (PMID 35370655, 2022). "The results showed that the mutation rate of CSTF2 was less than 5% in varieties of carcinoma, and the deep deletion was lower." (PMID 35370655, 2022). "We investigated whether the expression of CSTF2 is associated with the level of immunoinvasion in different types of cancer." (PMID 35370655, 2022). "In addition, CSTF2 was associated with multiple tumor immune infiltrates in a wide range of cancers, and its high expression was associated with multiple immune checkpoints; therefore, it could serve as a potential target for many drug molecules." (PMID 35370655, 2022). "Cleavage Stimulation Factor Subunit 2 (CSTF2) is known to influence tumor development across multiple cancer types." (PMID 39989603, 2025). "Previous analyses of tumor and matched normal control samples have identified CSTF2 (CstF64) as a potential pivotal regulator of 3′ UTR shortening across a subset of human cancers." (PMID 39375704, 2024). "In the current study, we demonstrated that CSTF2 is highly expressed in tumor tissues compared with that in normal tissues in a variety of malignant tumors based on the TCGA pan-cancer database." (PMID 35875122, 2022). "All in all, these results indicate that the overexpression of CSTF2 promotes cancer cell proliferation, migration, and invasion in HCC cells." (PMID 35875122, 2022). "Altogether, it appears that the high expression of CSTF2 activates many cancer-related pathways and cell-cycle and cell-proliferation-related pathways, contributing to the growth and development of HCC." (PMID 35875122, 2022). "We found that CSTF2 was highly expressed in plenty of cancers by analyzing the Tumor IMmune Estimation Resource (TIMER) database." (PMID 35875122, 2022). "Lung tumor cells prefers to use the shorten length transcripts of FGF2 (A) and MAP4K4 (B) compared to para-cancer tissue cells, and knocking-down of CSTF2 expression in H460 cells leads to extended length of transcripts for both FGF2 and MAP4K4 genes." (PMID 31391087, 2019). "Knocking down CSTF2 expression in H460 cells results in 3′UTR elongation of genes that was identified to be with shortened length in cancer tissues." (PMID 31391087, 2019). "Of interest, we detected higher protein expression of CSTF2 in six NSCLC cancer cell lines versus normal lung HFL1 cell line." (PMID 31391087, 2019). "In addition to further confirming the regulation of CSTF2 expression in cancer cell function, studies should also focus on the interaction between CSTF2 expression and a variety of drugs in the future to provide new ideas for the treatment of tumor patients." (PMID 35370655, 2022). "CSTF2 may play an important role in the activation of some oncogenes by altering the 3′-UTR length of oncogenes in cancer cells." (PMID 35370655, 2022). "Furthermore, CSTF2 was found to be highly expressed in NSCLC cells, and was deemed to regulate NSCLC progression by modulating the 3’-UTR length of cancer-associated genes." (PMID 35412944, 2022). "Although CSTF2 expression was significantly associated with immunoinvasion in a variety of cancers, the results suggested that CSTF2 did not play a decisive role in the tumor microenvironment during the development and progression of cancer." (PMID 35370655, 2022). "We then evaluated the effect of CSTF2 on prognosis in cancer patients." (PMID 35370655, 2022). "We have analyzed the functional role that CSTF2 may play in a variety of cancers and evaluated its potential as an anticancer drug target." (PMID 35370655, 2022).
cancer (continued). "We plotted the ROC curve of CSTF2 in a variety of cancers, and the results showed that CSTF2 had a strong diagnostic efficacy in a variety of tumors, indicating that the expression of CSTF2 could distinguish tumors from non-tumors." (PMID 35370655, 2022). "However, cleavage stimulation factor subunit 2 (CSTF2) was found to play a more critical regulatory role across cancers." (PMID 35370655, 2022). "CSTF2 may act as an oncogene to regulate the length of the 3′ non-coding region (UTR) of cancer-related genes in NSCLC." (PMID 35370655, 2022). "Therefore, in our study, the effects of CSTF2 on DNA mismatch repair and methylation in various cancer tumors were analyzed via a pan-cancer analysis, and on immune infiltration in the tumor microenvironment, as well as its value as an immune checkpoint." (PMID 35370655, 2022). "As a key regulatory molecule in the nucleus, the regulatory function of CSTF2 in many cancers is still unknown." (PMID 35370655, 2022). "Of these established cancer cell lines, H460 cells showed highest expression level of CSTF2." (PMID 31391087, 2019). "Alternative polyadenylation (APA) site-switching of 3′UTRs is prevalent in NSCLC, and CSTF2 may serve as an oncogene regulates the 3′UTR length of cancer related genes in NSCLC." (PMID 31391087, 2019). "However, there are few reports on the regulatory role and function of CSTF2 in pan-cancer." (PMID 35370655, 2022). "Apart from the four genes, other genes such as FBXL19, CSTF2, ZC3H11A, CRTC1 and MAGI3 influenced the formation and progression of human cancers with either carcinogenic or tumor-suppressive function." (PMID 30640723, 2019). "Our data also revealed the potential roles of polyadenylation processing protein, CSTF2, on the shortness of 3′UTR of these cancer-related genes." (PMID 31391087, 2019). "Recently, some studies have focused on the role of some mRNA 3′ end-processing factors in cancer, including FIP1L1, CSTF50, CSTF2 and Neo-PAP." (PMID 24358221, 2013). "Our results indicated that CSTF2 could affect the IC50 value of multiple drugs, suggesting that CSTF2 may affect the therapeutic effect of multiple drugs on cancer patients, and thereby affect the prognosis of cancer patients." (PMID 35370655, 2022). "Putative cancer drivers with a propensity to carry clonal SCNAs were an android receptor gene, the RNA gene XIST, the BRCA1 binding partners RBBP7 and NCOA2, a BRCC3 metaloprotease unit of the BRISC complex and CSTF2 that prevents inappropriate RNA processing at sites of DNA repair." (PMID 26632267, 2015). "We hypothesized that CSTF2 did not directly affect the response of immune cells to cancer cells but might influence the therapeutic effect of drugs on tumors, and therefore, indirectly affect the prognosis of cancer patients." (PMID 35370655, 2022).